CD44 (CD44 molecule (IN blood group))
Diseases named in the same sentence as CD44 in open-access papers (continued):
Sharing a sentence is not in itself a finding about the gene and the disease.
endometrial cancer (continued). "In the present study, CD133 and CD44, especially CD44, were upregulated in endometrial cancer cells in tumorsphere formation assay, suggesting that stemness is increased in this cancer stem cell model." (PMID 34831139, 2021). "Here, to efficiently target endometrial cancer, hyaluronic acid, which naturally binds to the CD44 protein was attached to the surface of nanoparticles and tested on microtissues or spheroids to better model a tumor and understand drug delivery performance." (PMID 34439185, 2021). "Using 3D models for endometrial cancer allows the elucidation of nanoparticle performance and CD44 targeting, likely through penetration and retention within the tumor model." (PMID 34439185, 2021). "SAHA encapsulation within F127 micelles functionalized with a surface hyaluronic acid moiety, was developed to target endometrial cancer cells expressing elevated levels of CD44." (PMID 34439185, 2021). "Using CD133+/CD44+ cancer stem cells-like isolated from the JEC endometrial cancer cell line they found an increase in autophagy relative to parental endometrial cells." (PMID 31850214, 2019). "In summary, the combined expression of ALDH1 and CD44 has been shown to identify subtypes of endometrial cancer with poor prognosis." (PMID 30372483, 2018). "Correlation of combination of ALDH1 and CD44 expression score with clinicopathological features in endometrial carcinoma." (PMID 30372483, 2018). "Correlation of ALDH1 and CD44 expression score with clinicopathological features in endometrial carcinoma." (PMID 30372483, 2018). "For example, CD44, a main adhesion receptor for hyaluronan, has been reported to be up-regulated in curettage and postoperative specimens of endometrial cancer." (PMID 26849234, 2016). "In endometrial cancer the expression of CD44 was significantly more intensive than in normal endometrium." (PMID 25129125, 2015). "The aim of the study is to assess a possible role of the CD44 as a marker of invasion in endometrial cancer, both at the moment of preoperative workup and final staging." (PMID 25129125, 2015). "An increased expression of CD44 in endometrial cancer suggests its possible role in pathogenesis of this disease, however, it doesn’t seem to be crucial." (PMID 25129125, 2015). "Adhesive molecules like CD44 are well defined key players in the metastatic cascade in many cancers, including endometrial cancer." (PMID 25129125, 2015). "High expression of suggested endometrial cancer stem cell markers is not indicative of aggressive disease, notably high expression of CD44 is linked to better clinical outcome." (PMID 39888143, 2025). "CD133/CD44+ endometrial cancer cells were able to form tumor spheres, with high chemoresistance." (PMID 40804837, 2025). "Other studies in endometrial cancer have reported CD44 expression." (PMID 38893151, 2024). "The use of various micro-RNAs (miRNAs) targeting the Notch pathway hindered the proliferation of the CD44/CD133-positive subpopulation in endometrial cancer (miRNA134), limited the expression of vimentin (VIM), reduced EMT, and decreased tumour formation and invasiveness (miRNA-34a)." (PMID 38539419, 2024). "Endometrial cancers are known to have more of the cell surface protein CD44 than healthy tissues." (PMID 34439185, 2021). "In addition it was found that the estrogen induced gene (EIG121) promoted both autophagy and cell survival in the subpopulation of CD133+/CD44+ cells and normal endometrial cancer cells." (PMID 31850214, 2019). "The combination of ALDH1 and CD44 could be a promising marker for developing additional targeted therapy for severe endometrial cancers." (PMID 30372483, 2018). "CD44, a transmembrane protein, has been shown to be a reliable stem cell marker based on its ability to isolate a sub-population of cells displaying stem cell properties from normal human endometrial tissue and endometrial carcinomas." (PMID 30372483, 2018).
endometrial cancer (continued). "Taken together, these data suggest that CD44 may be a common gene that is positively regulated by NMU signaling in diverse endometrial cancer cells." (PMID 26849234, 2016). "Taken together, our data suggest that activation of NMU signaling can positively contribute to the enhancement of growth factor-driven mesenchymal transition of endometrial cancer cells and that this potentially happens by sustaining the expression levels of CD44." (PMID 26849234, 2016). "From a clinical point of view, the analysis of LYVE1 and CD44 expression in endometrial carcinomas may help to identify patients with poor prognosis who may benefit from adjuvant therapies." (PMID 20374665, 2010). "In 102 endometrial carcinoma cases, CD44 was immunohistochemically detected in 94 cases (92.2%)." (PMID 20374665, 2010). "In vitro studies using breast and endometrial cancer cell lines revealed that hormonal treatments, such as estradiol, tamoxifen, and GnRH analogs, modulated solCD44 levels variably, suggesting hormone-specific regulation of CD44 isoform secretion and a complex relationship with therapeutic response." (PMID 41440277, 2025). "The purpose of this study was to investigate the correlation between stemness markers (CD44 and CD133) and prognostic value in endometrial cancer (EC)." (PMID 40804837, 2025). "The increased expression of CSC-related markers, including CD44, CD133, ALDH1A1, and NANOG, in spheroid cells of endometrial cancer translates into enhanced tumorigenicity." (PMID 38539419, 2024). "In EC, multiple studies have defined CD44 and CD133 as surface markers of endometrial cancer tumor stem cells." (PMID 38706601, 2024). "A decreased Dicer level increased the expression of the cancer stemness markers CD44, Aldh1, OCT, and Nanog and promoted the self-renewal of endometrial carcinoma cells." (PMID 35951366, 2022). "The panel included previously reported endometrial cancer stem cell markers (CD44, ALDH1 and CD133), normal endometrial stem cell markers (SOX9 and CD15) and universal stem cell marker." (PMID 39888143, 2025). "CD44, transglutaminase 2 (TGM2), and epithelial cell adhesion molecule (EpCAM) were identified as novel plasma markers for endometrial cancer diagnosis using the MAGPIX® System, which employs magnetic nanoparticles coated with antibodies and requires a tiny sample volume (25 μL)." (PMID 41440277, 2025). "Interestingly, Lin and co-workers recently described a NMU-NMUR2-mediated modulation of CD44 and RAC1 expression in endometrial cancer cells." (PMID 28423716, 2017). "With CD44 playing as an auxiliary receptor in promoting growth factor receptor activities, this explains how NMU signaling also tightly controls the intensity of EGFR-driven and TGFβ receptor-driven EMT in endometrial cancer cells." (PMID 26849234, 2016). "To date, CSC markers of endometrial cancer have been identified, including CD133, CD44 and ALDH1." (PMID 26506848, 2015). "The staining of CD44 was stronger in endometrial carcinoma tissue with LYVE1+ lymphatic vessels than without LYVE1+ lymphatic vessels." (PMID 20374665, 2010). "Our data indicate that the expression of CD44 isoforms, while obviously playing a role in the functional changes of normal endometrium, is not an adverse predictive factor in endometrial cancer." (PMID 9569051, 1998). "Therefore, we can not exclude the possibility that the impairment of SRC activity can contribute directly, or has a synergistic effect with the decrease of CD44 co-receptor level, to dampen the EGF-induced or TGFβ1-induced mesenchymal marker expression in the NMU-knockdown endometrial cancer cells." (PMID 26849234, 2016). "To evaluate the effect of Piwil1 in the acquisition of stem-like properties of endometrial cancer cells, we first studied whether the transfected cells created any shift in the patterns of expression of endometrial cancer stem cell markers, such as CD133, CD44 and ALDH1." (PMID 26506848, 2015).
endometrial cancer (continued). "Similarly, the absence of endometrial cancer cells with CD133+/CD44+ phenotype has been described." (PMID 38893151, 2024). "Nevertheless, another study suggested that CD44 and CD133 may be involved in the early stages of endometrial cancer development, but not the late ones, since CD133 expression is higher during the early tumor stage (FIGO I-II) compared with those of FIGO III to IV stage disease." (PMID 34063525, 2021).
viral infection (31 papers, 2010 to 2025). "Recently, the association between CD44 and viral infection has attracted much attention." (PMID 34515624, 2021). "Given the existing scientific literature also describes the role of tobacco and various viral infections in elevating PD-L1 and CD44 expression, these factors should also be investigated in future studies to obtain comprehensive insights." (PMID 39148690, 2024). "Resident memory T cell markers (CD44, CD62L, CD69 and CD11a) were also analysed to characterise the TRM population, previously associated with protection against viral infection." (PMID 33549390, 2021). "The frequency and numbers of CD44+CXCR5+ TFH cells were significantly diminished in Mettl3fl/flCd4-Cre mice compared with those in their control littermates on day 8 post viral infection." (PMID 33637761, 2021). "Cells that responded to viral infection had increased surface display of the activation markers such as CD44 and program death 1 (PD1), demonstrating a fresh recruitment of these cells in the course of the infection." (PMID 30388704, 2018). "The diverse physiological activity of CD44 is manifested in the pathology of a number of diseases including cancer, arthritis, bacterial and viral infections, interstitial lung disease, vascular disease, and wound healing." (PMID 25954275, 2015). "CD44 is involved in both physiological and pathological processes, including cell migration, adhesion, proliferation, tumorigenesis, and viral infection." (PMID 40544280, 2025). "Besides, we found that CD44 was closely related to virus infection including Coronavirus (also enriched in DDIT4), Epstein-Barr virus, Hepatitis B and Human papillomavirus." (PMID 38711596, 2024). "For example, CD44+ CSF EVPs elevated in viral infection may have possible activity as an adhesion molecule to aid in the migration of lymphocytes to the CNS." (PMID 37622115, 2023). "Thus, we employed a viral infection approach to specifically target CD44 in hippocampal astrocytes to unravel its function in epileptogenesis." (PMID 37296604, 2023). "When samples were grouped into viral vs. non-viral, EVP-associated CD40 and CD44 signals were elevated in those with virus infection (p = 0.0413 and p = 0.0176, respectively)." (PMID 37622115, 2023). "The complex role of CD44 in viral infection of different families and genera is highlighted." (PMID 36366532, 2022). "Similarly, the expression of CD44 and PAI-1 (encoded by SERPINE1) was also increased in the intestines of piglets during viral infection." (PMID 34515624, 2021). "Information about placental injury in COVID-asymptomatic women is scarce, so we investigated whether this viral infection has a significant impact on cluster of differentiation 44 (CD44), osteopontin (OPN), and cyclooxygenase-2 (COX-2) placental inflammatory markers." (PMID 39337033, 2024). "Thus, intranasal boosting immunization can substantially promote airway CD45+ and CD4+CD44+ T lymphocyte accumulation which may act immediately upon virus infection." (PMID 38987276, 2024). "Cul4b deficiency resulted in a decrease of CD44+CD8+ effector/memory T cells in steady-state, prompting us to explore whether Cul4b plays a role in CD8+ T-cell expansion and effector/memory T cell maintenance following viral infection." (PMID 37925424, 2023). "Hence, our study is the first to report the role of CD44 in protecting the intestine against viral infection, suggesting that CD44 could be a potential antiviral protein for novel interventions in intestinal coronavirus infection." (PMID 34515624, 2021). "CD44-expressing CD4+ and CD8+ T cell populations were also expanded by SCFA treatment during viral infection." (PMID 37865711, 2023). "On day 3 post viral infection, SMARTA CD4+ T cells of both genotypes showed similar upregulation of T-cell activation markers CD69 and CD44, and downregulation of CD62L." (PMID 33637761, 2021).
viral infection (continued). "Compare to mock-infected group, the quantity of intracellular CD44 and PAI-1 protein showed an increasing trend after viral infection." (PMID 34515624, 2021). "CD44+SLAMhi TH1 cells and CD44+SLAMlo TFH cells were sorted from Mettl3fl/flCd4-Cre mice and their Ctrl littermates on day 8 post viral infection and subjected to RNA-seq analysis." (PMID 33637761, 2021). "The CD44 and CD133 expression increased with the grades of inflammation and stages with fibrosis upon virus infection." (PMID 32471201, 2020). "During immune response to a viral infection, primed CD8+ T effectors exhibit upregulated CD44, downregulated CD62L, and high CD25 levels, whereas naive CD8+ T cells exhibit CD44low, CD62Lhigh, and CD25−." (PMID 32921633, 2020). "To document higher replication efficiency of GLV-1h68 strain in sorted CD44+CD24+ESA+ in comparison to CD44+CD24-ESA+ cells, we performed a virus infection followed by a replication assay." (PMID 22901246, 2012). "CD44+CD4+ and CD44+CD8+ T cells can secrete IL-2 and IFN-γ, with CD8+T cells potentially promoting activation of CD4+T cells through cytokine secretion, thereby exerting anti-infective effects against viral infections, intracellular bacteria, parasites, etc.." (PMID 40266142, 2025). "The presence or absence of CD44 does not affect poliovirus replication, and its role in viral infection has also been overlooked." (PMID 36366532, 2022). "Notably, Tfh cells from both virus infection and OVA immunization clustered in a separate node than CD4+CD44+GP66+ T cells, again in line with previous reports relating the TCR α chain to CD4+ cell fate decisions." (PMID 36028771, 2022). "CD44 has been shown to regulate effector T cell migration to sites of inflammation, but expression levels were similar on F5LΔP, F5B6, and F5L-sel−/− CD8+ T cells throughout the course of virus infection." (PMID 26804910, 2016). "In conclusion, JIMT-1 CD44+/CD24−/low are able at least to a limited extent to respond to exogenous IFN, however they have a dysfunction in initiation of endogenous type I IFN response upon virus infection." (PMID 21079774, 2010). "In conclusion, the normal mammary tissue CD44+/CD24−/low stem cells produced an intact IFN response to virus infection whereas both CD44+/CD24−/low CIC and non-CIC population were defective in IFN production when infected with an oncolytic adenovirus." (PMID 21079774, 2010). "Colocalization analysis of TLR9 and MyD88 to ER or endosomes in JIMT-1 CD44+/CD24−/low CICs showed that neither TLR9 nor MyD88 fully reaches endosomes in 4 h and 6 h respectively, whereas in the CD44−/CD24− non-CIC population localization became endosomal upon virus infection." (PMID 21079774, 2010). "As innate immune recognition of the oncolytic adenovirus seemed to be compromised in CIC we next assayed type I IFN production in response to virus infection by quantitative real time PCR in CD44+/CD24−/low normal stem cells, ArLa non-CIC cells and JIMT-1 CD44+/CD24−/low CICs." (PMID 21079774, 2010). "Furthermore, CD8+ (p < 0.0001), CD2+ (p < 0.0001), CD44+ (p = 0.0176), and CD40+ (p = 0.0413) EVP signals were significantly increased in the CSF from individuals with viral infections compared to those without." (PMID 37622115, 2023).
COVID-19 (29 papers, 2020 to 2026). A disease caused by infection with severe acute respiratory syndrome coronavirus 2. "We concluded that the blocking of HA adhesion to CD44 in the mouse model of COVID-19 improved survival and reduced readouts associated with pulmonary immunopathology while having no impact on viral titer." (PMID 41279061, 2025). "Neutrophils express high levels of CD44 and are implicated in the pathogenesis of severe COVID-19 through the production of proinflammatory cytokines, reactive oxygen species, and neutrophil extracellular traps (NETs) that can elicit hypercoagulation." (PMID 41279061, 2025). "Others have reported that the lymphopenia associated with COVID-19 could be a consequence of pulmonary recruitment and entrapment of lymphocytes, due to modification of adhesion molecules (CD44, LFA-1 and ICAM-1)." (PMID 33718270, 2021). "Here we show that the primary HA receptor CD44 contributes to COVID-19 pathology in a mouse model by mediating neutrophil infiltration/retention into the lungs." (PMID 41279061, 2025). "This indicates that neutrophils are responsible for at least a significant portion of the observed reduction in CD45 following treatment and are binding via CD44 to the pathological HA matrix in severe COVID-19." (PMID 41279061, 2025). "These cell adhesion molecules (ANXA1 and ICMA2), cytokine binding and receptor activity genes (CD44, CD45, CD47, CD74, and THBS1), and inflammatory genes (FPR1 and SELL) have been reported to be associated with COVID-19." (PMID 35172892, 2022). "We next pretreated LMVEC with an anti-CD44 antibody known to antagonize HA binding prior to incubation with HA purified from patients with COVID-19 and observed a similar inhibition of HA-induced barrier disruption to that in cells subject to CD44 knockdown." (PMID 34314391, 2021). "To test the hypothesis that hyaluronan deposition contributes to COVID-19 pathology through interactions with CD44, we intranasally inoculated mice with a mouse-adapted strain of SARS-CoV-2 that has been previously characterized." (PMID 41279061, 2025). "We hypothesized that increased HA deposition during COVID-19 increases CD44-mediated immune cell infiltration into lungs and results in more severe pathology." (PMID 41279061, 2025). "In this way CD44 may contribute to the degradation of HA into proinflammatory LMW fragments that have been seen in the lungs of severe COVID-19 patients, which occurs though an increase in the secretion of HA-degrading enzymes." (PMID 41279061, 2025). "Likewise, Gal-8 in the same manner upon binding to CD44 triggers a cascade of signaling pathways leading to the induction of proinflammatory cytokines in COVID-19 patients." (PMID 37676005, 2023). "CD44, receptor for hyaluronic acid (HA) in adult ECs and CACs, was also up-regulated in CACs + PCR cells, in agreement with recent findings reporting high circulating HA levels in COVID-19 patients compared to healthy controls." (PMID 35397534, 2022). "Finally, the incubation of human lung microvascular ECs with HA isolated from the plasma of COVID-19 patients, promoted endothelial barrier dysfunction in a CD44-depedent manner." (PMID 35397534, 2022). "Nonetheless, little attention has been paid to CD44 in COVID-19 treatment." (PMID 34163357, 2021). "CD44 inhibition reduces the IL-2 induced vascular leakage syndrome, revealing that CD44 may act as a potential target in COVID-19 treatment." (PMID 34163357, 2021). "However, contrary to our results, they indicate that numerous human milk proteins involved in the immune response were downregulated in response to COVID-19, like markers for neutrophil degranulation (CD44 and complement factor properdin (CFP)) and leukocyte migration." (PMID 37628421, 2023). "Further studies may determine if CD44 inhibitors can be of use to in COVID-19." (PMID 34163357, 2021).